RNF8 (ring finger protein 8)
Diseases named in the same sentence as RNF8 in open-access papers (continued):
Sharing a sentence is not in itself a finding about the gene and the disease.
cancer (continued). "By analyzing bulk RNA-seq data and scRNA-seq data, our results showed a direct correlation between RNF8 expression and immune cells such as monocytes and macrophages in various cancers." (PMID 35831895, 2022). "Based on pancancer-normalized mRNA abundance data of nine cancers, we trisected samples, and divided them into an RNF8 high-expression group and an RNF8-low expression group in different cancer types." (PMID 35831895, 2022). "Targeting of RNF8 not only suppresses or eliminates the metastatic capacity of cancer cells but also increases the sensitivity of cancer cells to anticancer drugs upon depletion of RNF8, which can greatly improve the efficacy of anticancer drugs." (PMID 33912571, 2021). "Collectively, these results suggest that RNF8 physically binds to and protects ATM-phosphorylated MDC1 from caspase-dependent proteolytic cleavage in BIN1-deficient cancer cells." (PMID 34948122, 2021). "For this purpose, RNF8 siRNA (si-RNF8) was transfected alone or co-transfected with si-MDC1 in BIN1-depleted cancer cells in the presence of cisplatin (2.0 μg/mL) for 72 h." (PMID 34948122, 2021). "Together, these findings depict the complex biology of RNF8 and suggest that the effects of RNF8 on cancer migration and invasion likely depend on the RNF8 target protein." (PMID 32042335, 2020). "Mutating the DOT1L K358 site to R358 renders DOT1L susceptible to degradation via an interaction with the E3 ligase RNF8 and this process inhibits cancer-cell metastasis." (PMID 32042335, 2020). "The results showed that these hub genes exhibited distinct expression patterns in different cancers, such as RNF8 in THYM, YPEL2 in LAML and E2F6 in DLBC, which indicated the potential relation of these genes with the corresponding cancer." (PMID 31709182, 2019). "Ubiquitination of H2A.X is less studied in cancer but the E3 ligases RNF168 and RNF8 have been implicated in cancer and genomic instability." (PMID 29495465, 2018). "More importantly, a relatively larger proportion of either cytoplasmic or nuclear expression of RNF8 is higher in lymph node metastases than in the corresponding primary cancers." (PMID 27259701, 2016). "The expression level of RNF8 either in cytoplasm or in nuclear is significantly higher in lymph node metastases when compared with the corresponding primary cancers (p = 0.014, p = 0.016, respectively)." (PMID 27259701, 2016). "Statistical analysis showed a significant increased expression of RNF8 in cancer tissues (P = 0.006)." (PMID 27259701, 2016). "We knocked down RNF8 using an adenovirus-mediated shRNA and detected decreased cancer cell survival post-IR following RNF8 knockdown." (PMID 26788910, 2016). "Notably, abnormal expression of BCKDK, phosphorylated RNF8 (p‐RNF8), and RAD51 are associated with cancer progression and patient outcomes." (PMID 40298908, 2025). "In addition, RNF8 promotes epithelial-to-mesenchymal transition and chemoresistance in cancer by stabilizing Twist, Akt, and Slug, as well as mammary tumorigenesis by preventing RNF8-mediated Notch1 degradation through RNF8 downregulation." (PMID 37468549, 2023). "Taken together, we speculated that RNF8 might function as a universal regulator of EMT in cancers, and its impacts on the expression of EMT-TFs might be the underlying mechanisms in regulating EMT." (PMID 37154586, 2023).
cancer (continued). "To investigate the possibility that RNF8 increases lenvatinib efficiency, we first detected lenvatinib sensitivity in cancer cell lines and discovered that lenvatinib killed Huh7 cells easily, whereas HCCLM3, HepG2 and SNU387 cells all seemed to be resistant to lenvatinib." (PMID 37154586, 2023). "We hypothesize that the inhibitory role of RNF8 in EMT and its enhancing effects on anti-cancer drugs orchestrate the protective effects of RNF8 deficiency in HCC, which indicates its potential in clinical application." (PMID 37154586, 2023). "Whether RNF8 regulates tumor-infiltrating immune cells and whether this regulation affects cancer status, such as progression or metastasis are unknown." (PMID 35831895, 2022). "Taken together, these findings revealed the potential correlation between RNF8 and tumor-infiltrating immune cells, which might provide new insight into RNF8’s functional heterogeneity in divergent cancers." (PMID 35831895, 2022). "Downmodulation of RNF8 also enhances cancer cell radiosensitivity." (PMID 35831895, 2022). "Recently, multiple reports have shown that RNF8 could be used as an important therapeutic target for cancer chemo/radiotherapy." (PMID 35831895, 2022). "In recent years, several studies have indicated that RNF8 promotes EMT via K63-linked ubiquitination and subsequent activation and stabilization of EMT-associated proteins, including TWIST, Slug, and β-catenin, in driving cancer metastasis." (PMID 34357122, 2021). "If ATM-phosphorylated MDC1 does not require RNF8 to mediate cisplatin resistance, we anticipated that the depletion of RNF8 alone would not change the si-MDC1-induced cisplatin sensitivity in BIN1-deficient cancer cells." (PMID 34948122, 2021). "A pan-cancer survival rate analysis was also performed to assess the prognostic values of these genes, and the results showed that these overlapping genes might be signatures in various cancers, such as RNF8 in KIRC, RB1 in OV and E2F6 in LIHC." (PMID 31709182, 2019). "However, RNF8 hyper‐accumulation is tumour‐promoting and positively correlates with genome instability, cancer cell invasion, metastasis and poor patient prognosis." (PMID 31613024, 2019). "We propose that the p97–ATX3 complex is the essential machinery for regulation of RNF8 homeostasis under both physiological and genotoxic conditions and that targeting ATX3 may be a promising strategy to radio‐sensitise BRCA‐deficient cancers." (PMID 31613024, 2019). "The role of RNF8 in DNA damage repair has been extensively studied, however there are no studies which associate RNF8 rs2284922 as playing a role in cancer susceptibility or drug response." (PMID 30071039, 2018). "Genomic instability and cancer susceptibility are increased in the absence of Mdc1, Rnf8, 53bp1 or Brca1." (PMID 21552324, 2011). "Thus, we believe that RNF8 could be an important target for further research in fighting against metastasis in cancers for clinical application." (PMID 37154586, 2023). "Consequently, because the role of RNF8 in the progression of other cancers remains unclear, it is important to clarify the function and mechanism of RNF8 in regulating the progression of cancer." (PMID 32549753, 2020). "Therefore, a potential anti-cancer target might exert its effect by suppressing the functional expression of RNF8." (PMID 26788910, 2016). "Our present findings indicate that WRAP53β and RNF8 are rate-limiting factors in the repair of DNA double-strand breaks and raise the possibility that upregulation of WRAP53β may contribute to genomic stability in and survival of cancer cells." (PMID 27310875, 2016). "Additionally, if other genotoxic anti-cancer agents, such as certain classes of chemotherapeutic agents, eliminate cancer cells via similar molecular mechanisms, knockdown of RNF8 may hypersensitize target cells to the anti-cancer treatment." (PMID 26788910, 2016).
cancer (continued). "For instance, the human demethylase JMJD1C was stabilized by interaction with RNF8 and recruitment of RAP80-BRCA1, and MDC1 was demethylated at Lys45 through JMJD1C binding to RNF8 and MDC1, promoting cancer cell sensitivity to IR153." (PMID 32355263, 2020). "A specific gene with highly differential expression, such as RNF8 in THYM, YPEL2 in LAML, and E2F6 in DLBC, indicates a strong correlation between this gene and the corresponding cancer." (PMID 31709182, 2019). "Overexpression of ubiquitin ligases including MDM2, COP1 and ARF-BP1 has been observed in human cancer, while downregulation of others such as FBW7 or Rnf8 promotes tumorigenesis." (PMID 22125490, 2011). "Among the studied 17 genes, this is the first report of promoter methylation for CpG sites in H2AX, RNF8 and CYCS in human cancer." (PMID 21092294, 2010). "In addition, batch gene set enrichment analysis showed that RNF8 was enriched in terms such as the MAPK signaling pathway, focal adhesion, and transcriptional misregulation in cancer." (PMID 35831895, 2022). "In this study, we have found RNF8 protein expression is significantly higher in primary cancers than that of the matched noncancerous tissues." (PMID 27259701, 2016). "However, the understanding of RNF8 remains limited due to the lack of its interactome reference map and comprehensive analysis of RNF8 in diverse cancers, which underscores the need to map the interactome of RNF8 via high-throughput methods." (PMID 35831895, 2022). "Thus, CLIP-170, CHFR, and RNF8 all have pathological functions in cancer, and the potential interaction between CLIP-170 ubiquitination and CHFR or RING8 E3 ligases might have clinical implications, such as the therapeutic treatment of cancers." (PMID 36138017, 2022). "In addition, the role of RNF8 in immunology-related processes such as neutrophil-mediated immunity and neutrophil activation, and whether these connections affect the role of RNF8 in cancer tissues have not been discussed and require further exploration." (PMID 35831895, 2022).
tumor (27 papers, 2010 to 2025). "RNF8 deficiency has been associated with tumor development, probably due to increased genomic instability." (PMID 34573315, 2021). "Interestingly, Rnf8−/− mice also demonstrated an increased risk for tumor development, suggesting that Rnf8 is a bona fide tumor suppressor." (PMID 23382699, 2013). "In addition, Rnf8-/- mice display increased genomic instability and higher risk for tumorigenesis, proposing that RNF8 is a novel tumor suppressor." (PMID 21774837, 2011). "To further assess the synergistic effect in vivo, we utilized an MMTV‐PyMT mouse TNBC model, which showed an enhanced BCKDK/p‐RNF8/RAD51 axis in tumor tissues compared to normal compartments." (PMID 40298908, 2025). "Our previous studies have shown that RNF8 is critical in tumor progression, treatment, and neurodegeneration." (PMID 40707433, 2025). "The remarkable distribution difference was more typical in RNF8−/− mice, cytokines in tumor center performed remarkably decreased." (PMID 37391451, 2023). "It suggests that the high expression of gal-3 in the tumor center and periphery from RNF8−/− mice is related with the degradation of gal-3 via the ubiquitin–proteasome system." (PMID 37391451, 2023). "Concerning its critical role in DNA damage, RNF8 has been regarded as a tumor suppressor for a long time." (PMID 37154586, 2023). "The current studies explore the effect of RNF8 on the progression and therapy resistance of tumor cells, based on the mechanisms related to DNA damage repair and genomic instability." (PMID 37391451, 2023). "In this study, we demonstrated that RNF8 is an important regulator of gal-3, RNF8 deficiency of the host led to increased gal-3 level in TME and promoted implanted tumor progression." (PMID 37391451, 2023). "IHC staining analysis demonstrated that IL-12 and IFN-γ positive cells in tumor center were increased in RNF8+/+ and RNF8−/− mice after LAC treatment." (PMID 37391451, 2023). "Nevertheless, LAC injection in tumor effectively liberated IL-12 and IFN-γ and thus elevating downstream chemokines CXCL-9 and CXCL-10, particularly in RNF8 deficient mice." (PMID 37391451, 2023). "Exactly, gal-3 expression in the tumor center was higher than that in the periphery especially in RNF8−/− host." (PMID 37391451, 2023). "We demonstrated that depletion of RNF8 in vivo induced gal-3 expression and suppressed immune cell infiltration as well as the cytokines recruitment in TME, leading to an increase the tumor progression compared with RNF8 wildtype (RNF8+/+) mice." (PMID 37391451, 2023). "Our results revealed a close relationship between RNF8 and neurodegenerative diseases or tumor-infiltrating immune cells using bulk RNA-seq and scRNA-seq datasets." (PMID 35831895, 2022). "In LICH, STAD, BRCA, CHOL and HNSC (Group 1), elevated expression of RNF8 was observed in tumor tissues and was related to poor prognosis." (PMID 35831895, 2022). "The tumor volume was measured every day after injection, and the results showed that silencing RNF8 significantly reduced the proliferation rate of HCT116 cells in vivo." (PMID 32549753, 2020). "The effect of RNF8 on tumor metastasis was assessed in immune-compromised female BALB/c mice (n = 6) by tail vein injection of MDA-MB-231-Luc-D3H2LN cells." (PMID 27259701, 2016). "With nude mice xenograft model, we found that shRNA mediated-downregulation of RNF8 reduced tumor metastasis in vivo." (PMID 27259701, 2016). "The xenograft model was done with nude mice to investigate the role of RNF8 in tumor metastasis in vivo." (PMID 27259701, 2016).
tumor (continued). "Western blots were performed to assess RNF8 expression in the tumor samples from the two groups on the 5th day; the results revealed that RNF8 expression was decreased in the shRNF8-treated group compared to the shNull-treated group." (PMID 26788910, 2016). "The analysis of RNF8- and RNF168-deficient mice further supports a role of these key E3 ligases in tumor suppression." (PMID 26442100, 2015). "The impacts on PFS further supported the significance of RNF8 in tumor progression." (PMID 37154586, 2023). "We observed significantly lower RNF8 expression in GBM when compared to the non-tumor tissues." (PMID 37468549, 2023). "Recent studies have also reported the positive role of RNF8 in promoting tumor progression." (PMID 35428760, 2022). "Notably, analogously to RNF8, Usp3-deleted mice develop a broad spectrum of tumor types with a latency of 1 year of age." (PMID 26442100, 2015). "However, recent studies have reported that RNF8 might promote tumor progression in colorectal cancer and nasopharyngeal cancer." (PMID 37154586, 2023). "We also revealed the unrecognized relationship between RNF8 and neurodegenerative diseases or tumor-infiltrating immune cells, and validated the direct binding between RNF8 and YBX1, and showed that RNF8 catalyzed the ubiquitination of YBX1, showing that RNF8 might be a crucial regulator of YBX1." (PMID 35831895, 2022). "Western blot analysis showed increased levels of BCKDK, p‐RNF8S157, and RAD51 proteins in tumor tissues compared to their adjacent normal tissues, suggesting enhanced activity of the BCKDK/p‐RNF8/RAD51 regulatory pathway in clinical tumor tissues." (PMID 40298908, 2025). "Consistent with in vitro results, RNF8 phosphorylation and RAD51 protein levels were increased in Olaparib‐treated tumor samples and were rescued by BCKDK knockdown." (PMID 40298908, 2025). "ATM is a known gene active in radiation-induced DNA damage repair, but LIG4 and RNF8 are less well known genes in radiation response in HNSCC, although their role in DNA repair has been well studied in other tumor models." (PMID 40768535, 2025). "Results revealed that CD3 expression was significantly higher in tumor periphery than center, moreover, CD3 expression in both tumor center and periphery from RNF8−/− mice was more obvious lower than from RNF8+/+ mice." (PMID 37391451, 2023). "In this study, B16F10 cells were injected subcutaneously into RNF8+/+ and RNF8−/− mice, and then LAC was injected into tumor center." (PMID 37391451, 2023). "Consistently, RNF8 knockout of host resulted in significantly decreased IL-12 and IFN-γ in the tumor, which was directly related to gal-3 elevation." (PMID 37391451, 2023). "Subsequently, we injected stable RNF8 knockdown or control 22Rv1 cells subcutaneously into male NOD/SCID mice and measured the tumor volume every week." (PMID 35428760, 2022). "Among these were genes with tumor-suppressive activities such as CUL2, CTNNA3, and RNF8 (ST2B)." (PMID 40723280, 2025). "Subsequently, immune cells subsets in tumor of RNF8+/+ and RNF8−/− mice were investigated by CyTOF." (PMID 37391451, 2023). "The CD3+CD4+, CD3+CD8+ and NK cells in tumor from RNF8−/− mice were obviously lower than RNF8+/+ mice, LAC treatment significantly increased infiltration of CD3+CD4+, CD3+CD8+ and NK cells in tumors both in RNF8+/+ and RNF8−/− mice." (PMID 37391451, 2023).
tumor (continued). "The expression of HIF-1α in tumor center was increased compared with tumor periphery, however, the expression of HIF-1α has no significant change in tumor-beared RNF8+/+ and RNF8−/− mice." (PMID 37391451, 2023). "We hypothesized that the effects of RNF8 on EMT and drug sensitivity orchestrate its tumor-promoter role in HCC, which could kill two birds with one stone." (PMID 37154586, 2023). "However, quantitative analysis of IHC data showed that RNF8 levels was not significantly correlated with patient tumor stage and prognosis." (PMID 40298908, 2025). "BCKDK‐overexpressing and RNF8‐silenced MDA‐468 tumors expressing RNF8WT or RNF8S157D, but not RNF8S157A, could restore tumor volume and mass, under Olaparib treatment." (PMID 40298908, 2025).